LEP (leptin)
Diseases named in the same sentence as LEP in open-access papers (continued):
Sharing a sentence is not in itself a finding about the gene and the disease.
Obesity (continued). "The effects of leptin on T cell number and function have been extensively reviewed and will not be discussed in depth here, yet special consideration must be given to the role of leptin in mediating T cell changes in malnutrition or obesity." (PMID 25157251, 2014). "We demonstrated that flurbiprofen, a nonsteroidal anti-inflammatory drug (NSAID), exhibited chaperone activity, which reduced protein aggregation and alleviated ER stress-induced leptin resistance, characterized by insensitivity to the actions of the anti-obesity hormone leptin." (PMID 24421337, 2014). "It is now understood that failure of leptin in the vast majority of obesity may be due to leptin resistance." (PMID 25309775, 2014). "The circulating concentration of leptin correlates with the level of obesity." (PMID 24959279, 2014). "Pathological damage of Leydig cells, oxidative stress in testis tissue, and high level of leptin may provide some evidence to clarify the mechanisms of male SH in obesity." (PMID 24829619, 2014). "In obesity, there is an increased production of free fatty acids, angiotensinogen, leptin, resistin and inflammatory mediators that might be involved in mechanisms of obesity-associated microvascular dysfunction." (PMID 25036223, 2014). "Rodent models of HF diet-induced obesity are characterized by inflammation in both peripheral tissues and in the hypothalamic regions critical for energy homeostasis, which is considered an important mechanism linking obesity to glucose intolerance, insulin resistance and leptin resistance." (PMID 24675731, 2014). "However, its effect was modest in obese patients (Mantzoros ' Flier, 2000), most of whom were considered to be in a state of leptin resistance and unable to adequately respond to the anti-obesity signals of leptin (Münzberg ' Myers, 2005)." (PMID 24421337, 2014). "Several obesity-related host factors can influence breast tumor initiation, progression, and/or response to therapy including insulin, insulin-like growth factor-1, leptin, adiponectin, steroid hormones, cytokines, vascular regulators, and inflammation-related molecules." (PMID 25110685, 2014). "However, most previous studies have focused on the relationship between leptin and obesity, and each component of MS, instead of a cluster of MS components." (PMID 24444121, 2014). "Genetic defects in leptin and leptin receptors result in severe early onset obesity in children." (PMID 25412152, 2014). "Defective central leptin signaling is also associated with enhanced endocannabinoid tone independent of obesity." (PMID 25168868, 2014). "Both adiponectin and leptin levels are known to be altered in obesity." (PMID 25105135, 2014). "Earlier studies have shown that variants in TCF7L2 were positively selected, and were associated with BMI and levels of ghrelin and leptin; however, no general enrichment of adaptive variants in type 2 diabetes- and obesity-associated loci have been found." (PMID 25222615, 2014). "In the present study, we hypothesized that leptin may activate UPR and protect against ER stress associated with obesity." (PMID 25403445, 2014). "Common forms of obesity are characterized by elevated circulating leptin." (PMID 25167881, 2014). "Moreover, studies have shown the severity of obesity to be directly proportional to the concentration of circulating leptin." (PMID 25309775, 2014). "Recent research suggests that leptin may be an important factor linking obesity, the metabolic syndrome, and cardiovascular disorders." (PMID 24741591, 2014). "The obese JCR rats develop obesity due to over eating as a result of defect in leptin signalling." (PMID 25222487, 2014). "Besides the leptin gene receptor, polymorphism possibly intermeddles with the regulation of body weight, obesity, fat mass distribution, serum leptin levels, glucose homeostasis, and diabetes, among others." (PMID 24772364, 2014).
Obesity (continued). "JTT-551, a novel developed PTP1B inhibitor, shows not only an improvement of glucose metabolism but also an antiobesity effect possibly by enhancement of leptin signaling and could be useful in the treatment of type 2 diabetes mellitus and obesity." (PMID 24987707, 2014). "This study was to investigate the prevalence of single nucleotide polymorphisms (SNPs) in leptin gene LEP (A19G and G2548A) and leptin receptor gene LEPR (K109R and Q223R) and their association with fasting plasma leptin level (PLL) and obesity in a Malaysian suburban population in Kampar, Perak." (PMID 24947733, 2014). "In mice undergoing leptin glycopeptide treatment, several obesity-related pathologies (i.e., abnormal metabolic profile and liver histology as well as infertility) are normalized while unglycosylated leptin protein therapy does not show similar positive treatment outcomes." (PMID 25152873, 2014). "In the context of obesity, adipokines such as leptin may promote mTOR activity to promote effector T cell generation and contribute to inflammation." (PMID 25157251, 2014). "Furthermore, we found that DNA methylation of the leptin promoter varied with the process of obesity." (PMID 24923522, 2014). "It is notable that administration of leptin corrects many diabetic manifestations in ob/ob mice, and the correction of hyperinsulinemia and hyperglycemia occurs before the effect on obesity, indicating that obesity plays a secondary role in the pathogenesis of diabetic manifestations in this model." (PMID 24809394, 2014). "The physiological function of leptin is to prevent obesity in excessive flow of food into the body." (PMID 24410812, 2014). "Leptin resistance is the process occurring in human obesity and in several models of rodent obesity in which synthesis and secretion of leptin are increased, while inhibition of feeding or activation of energy expenditure by leptin are decreased." (PMID 24498181, 2014). "Further investigations into the inhibitory effects of leptin at high concentrations may reveal the unknown mechanisms in the connection between obesity and postmenopausal breast cancer." (PMID 24959279, 2014). "Moreover, high blood concentrations of leptin are strongly correlated with obesity, and it was observed that these concentrations decrease with weight loss." (PMID 24387137, 2014). "Leptin is an adipocyte-derived hormone (adipokine) under the control of the obesity (ob) gene." (PMID 25125800, 2014). "Obesity could affect breast carcinogenesis by autocrine and paracrine actions mediated by two major adipokines: leptin and adiponectin." (PMID 24716804, 2014). "Long-term studies would assess whether those molecules can become valuable drugs against leptin resistance and obesity." (PMID 25352831, 2014). "Although not studied in the clinical setting, any possible mechanical or metabolic advantage the heart develops in response to the intermittent hypoxia component of OSA may be attenuated by the presence of obesity or leptin insensitivity." (PMID 24771695, 2014). "The regulation of accumulation and function of PPARγ+ Treg by leptin and adiponectin represents a potentially valuable therapeutic pathway that may, in the future, be targeted in order to regulate obesity-related pathologies." (PMID 25477880, 2014). "Importantly, both obesity and high leptin levels have been observed in OSA patients, who present a high risk to develop arterial hypertension than non-obese OSA patients." (PMID 25009507, 2014). "The resulting hyperinsulinaemia in turn could exacerbate obesity and further increase leptin levels, resulting in a positive feedback loop that could promote the development of diabetes." (PMID 25276234, 2014). "Similar to the relationship between the Treg cells and leptin, there may be other factor(s) that can also maintain ATDCs in obesity adipose tissues." (PMID 24642966, 2014).
Obesity (continued). "Furthermore, administration of vaspin suppresses leptin, TNFα, and resistin, reduces food intake, and improves glucose control and insulin sensitivity in obesity." (PMID 24899788, 2014). "One possible mechanism for obesity’s harmful effects on the immune system could be the increased levels of leptin in the blood." (PMID 24939238, 2014). "Following the same lines of evidence, in a study of 284 volunteers with various levels of waist to hip ratio, the differences in blood pressure by LEPR variants remained significant after adjusting for the influence of obesity and body fat distribution, as well as insulin and leptin." (PMID 24772364, 2014). "The most favored hypothesis attributes the elevated TSH levels in obesity to increased leptin-mediated production of pro-thyroid releasing hormone." (PMID 25214835, 2014). "Leptin, a main cytokine coded by obesity gene and secreted by adipocytes, especially higher levels in obese patients, is essential, and it acts not only in the arcuate hypothalamus nucleus as a satiety signal, but also in the inflammatory and endothelial systems." (PMID 24466027, 2014). "Indeed, obesity has long been recognized to be a risk factor for tumorigenesis, and accumulating evidence suggests that leptin is a potential link between obesity and cancer development." (PMID 24867470, 2014). "Since leptin exerts an anti-obesity effect, it was initially expected to be an anti-obesity drug." (PMID 24421337, 2014). "To define the gene expression profile changes during the progression to NASH, we used hepatic samples from young (16-week-old) and old (48-week-old) mice from three obesity models: hyperphagic ob/ob and db/db mice with disruption of leptin signalling and wt C57BL/6J mice fed a HFD." (PMID 24913135, 2014). "Sleep deprivation may lead to obesity via several mechanisms; including increased sympathetic activity, increased cortisol and ghrelin levels, and decreased leptin levels." (PMID 25437226, 2014). "By regulating food intake and obesity, leptin indirectly impacts insulin sensitivity, but emerging evidence suggests that leptin may also directly regulate insulin signaling." (PMID 25674466, 2014). "Hypothetically, as with the development of resistance to leptin’s appetite suppressing functions, patients with obesity may, overtime, down-regulate the immune activation attributable to leptin." (PMID 24939238, 2014). "Increased serum concentrations of leptin are also associated with an increased risk of myocardial infarction and stroke, independent of obesity and other traditional cardiovascular risk factors." (PMID 25375161, 2014). "Most models of obesity exhibit an increase in leptin and a decrease in adiponectin." (PMID 24744913, 2014). "A study on a mouse model of obesity showed that leptin could prevent respiratory depression suggesting that lower leptin levels or activity may induce hypoventilation in some obese subjects." (PMID 24982545, 2014). "JTT-551 shows an antiobesity effect possibly by enhancement of leptin signaling and could be useful in the treatment of type 2 diabetes and obesity." (PMID 24987707, 2014). "Since FAAH is regulated by both insulin and leptin, we hypothesise that factors such as insulin and leptin resistance in obesity oppose any further increases in FAAH activity and that MGL must be under other regulating factors." (PMID 24593280, 2014). "Estrogen regulates the action of leptin in endothelial cells; it has been suggested that patients with psoriasis and hyperleptinemia tend to be of female gender and that those female patients manifested obesity and metabolic syndrome." (PMID 24600521, 2014). "It has been suggested that high circulating leptin and low adiponectin predict asthma independent of obesity and that low leptin and high adiponectin are associated with stable COPD." (PMID 24891763, 2014).
Obesity (continued). "However, an interconnected influence of leptin was lost after adjustment for BMI as an independent variable in the regression equation, probably due to obesity." (PMID 24981337, 2014). "We further investigated the effects of flurbiprofen on body weight loss using ob/ob mice, another model of obesity, which have no functional leptin and were previously shown to be in a state of ER stress." (PMID 24421337, 2014). "Based on these findings, leptin concentrations may be considered a marker for the extent of body weight, obesity, and fat mass in humans." (PMID 24868483, 2014). "Leptin administration has been shown to increase satiety and satiation in mouse models of obesity as well as in humans with leptin insufficiency, suggesting that it may affect the secretion and/or function of such hormones to promote weight reduction." (PMID 24987413, 2014). "NSY mice had an extremely high level of leptin, as was reported in a number of obesity models." (PMID 25167881, 2014). "The lack of correlation with leptin may be attributable to decreased responsiveness to leptin in obesity." (PMID 25514415, 2014). "However, to date, no previous study has demonstrated an independent association of leptin with brachial artery FMD assessed by ultrasound, in human subjects with obesity and/or MetS." (PMID 24410779, 2014). "Due to its anti-obesity effects, leptin has attracted interest regarding treatments for obesity." (PMID 25403445, 2014). "In conditions of obesity, and particularly central obesity that favors insulin resistance and type 2 diabetes, leptin sensitivity is diminished owing to lower CNS leptin entry (decreased CSF: plasma leptin ratio) and defective LepRb signaling." (PMID 24109426, 2013). "There are two theories that relate leptin's cardiovascular effects to obesity." (PMID 23573411, 2013). "Thus, leptin gene therapy is expected to be an effective therapeutic option for obesity, and diabetes." (PMID 23579596, 2013). "In addition, obesity-induced leptin induces the overexpression of CD14 via activation of STAT3 signaling in Kupffer cells, resulting in a hepatic hyper inflammatory response to low-dose LPS, and plays a crucial role in the progression of NASH." (PMID 24192824, 2013). "ADN is secreted by mature adipocytes; however, in contrast to leptin, lower ADN levels are associated with obesity, insulin resistance, diabetes, and disordered lipid metabolism and exhibits anti-inflammatory properties that inhibit monocyte adhesion and macrophage function." (PMID 23520452, 2013). "In addition, leptin is considered a novel link between obesity, diabetes, cardiovascular risks and ventricular hypertrophy." (PMID 24354396, 2013). "Genetic disruption of AMPK specifically in POMC or AgRP neurons causes obesity or resistance to obesity, respectively, while the neurons themselves maintain the ability to respond to insulin and leptin but not glucose." (PMID 23550218, 2013). "We have previously shown that neonate male rats born to perinatally adequately nourished dams orally treated with physiological amounts of leptin throughout the suckling period are protected against the development of obesity and metabolic dysfunction in adulthood." (PMID 24312379, 2013). "The SOCS molecules might play an important role in the development of leptin resistance that is observed in the CNS and in the endocrine pancreatic beta-cells during obesity." (PMID 23579596, 2013). "One possible mediator of this protection is leptin, a hormone highly elevated in human obesity." (PMID 23957291, 2013). "All these data indicate that leptin could represent the molecular link between obesity and reduced number/function of Treg observed in this condition and on the basis of these data, one could predict that leptin might interact with the mTOR pathway." (PMID 24151494, 2013). "Leptin, a major adipocyte-derived adipocytokine, is a known biomarker of obesity." (PMID 23335226, 2013).
Obesity (continued). "The reason for gonadotropin resistance in obesity is unclear; however, alterations in serum and follicular concentrations of adipokine leptin might be involved." (PMID 23803145, 2013). "As obesity and infertility are common in animal models with impaired leptin responses, we hypothesized that Magel2-null mice may also respond abnormally to leptin." (PMID 23341784, 2013). "Moreover T regs were specifically reduced in the abdominal site in insulin-resistant models of obesity, with a mechanism related, at least in part, to the suppressive ability of leptin on T reg proliferation." (PMID 24084730, 2013). "In particular, leptin may be directly involved in colon tumorigenesis, or it may serve as a sensitive and robust marker of an obesity-induced adverse endocrine environment." (PMID 24198829, 2013). "A positive association between elevated leptin and history of myocardial infarction among men and women and stroke among women was independent of obesity in study on National Health and Nutrition Examination Survey (NHANES) data." (PMID 24455217, 2013). "Given the effects of leptin on the immune system and the lung, it is conceivable that obesity-related increases in leptin could initiate or worsen asthma." (PMID 24288549, 2013). "Obesity is a chronic metabolic disease, which is considered a public health problem that may lead to insulin resistance and increased serum leptin levels, affecting both developed and emerging countries." (PMID 23468891, 2013). "In obesity, the development of leptin resistance may result in a breakdown of the normal partitioning of surplus lipids in the adipocyte compartment." (PMID 23356701, 2013). "Leptin is an important signal providing information about energy stores in the fat mass to the central nervous system and circulating leptin concentrations are correlated with the extent of obesity." (PMID 23342013, 2013). "One explanation for this discrepancy is that ghrelin and leptin have mutually antagonistic effects on inflammatory cytokine expression in obesity and reduced leptin after ghrelin administration may involve in reduction of serum NO level." (PMID 23533447, 2013). "The results of the study suggest that the four cardiac hormones lead to significant reductions in hypothalamic leptin levels, which may be an important mechanism for alleviating leptin-induced hypertension in obesity." (PMID 24137236, 2013). "However, leptin levels are increased in obese subjects, with little or no impact to regulate energy homeostasis, which coined the well-established phrase “leptin resistance” in obesity." (PMID 24455420, 2013). "It is anticipated that, with a further understanding of the complex biology of LDD and its relationship with obesity, functional inhibition of the leptin signal may be a hopeful strategy for the prevention and treatment of LDD." (PMID 23335226, 2013). "Moreover, chronic CB1 blockade improves peripheral metabolic parameters of obesity, including a reduction in plasma levels of insulin and leptin." (PMID 24391536, 2013). "Thus, it seems that ghrelin has a protective mechanism including leptin resistance in setting obesity." (PMID 23533447, 2013). "Obesity amplifies the production of multiple adipokines, and it is possible that adipokines may offset the anti-arrhythmogeneic potentials of leptin, thereby increasing the risks of AF in obesity." (PMID 24354396, 2013). "Obesity is considered as an inflammatory status, because proinflammatory molecules, expressed by adipose tissue such as leptin, TNF-α, IL-6, TGF- β1, adiponectin and C-reactive protein, are increased in obese subjects, especially in females (mainly C-reactive protein and leptin)." (PMID 24028436, 2013). "CCDC80 is a secreted protein that regulates adipocyte differentiation, whereas DGAT2 is an enzyme that catalyzes the final step of mammalian triglyceride synthesis and may be involved in the mechanisms of obesity, insulin resistance, and leptin resistance." (PMID 23741331, 2013).